IL5 (interleukin 5)
Diseases named in the same sentence as IL5 in open-access papers (continued):
Sharing a sentence is not in itself a finding about the gene and the disease.
allergic asthma (continued). "For example, dupilumab, an anti‐interleukin 4 (IL4) receptor alpha monoclonal antibody, has already been approved for the treatment of atopic dermatitis and allergic asthma, while mepolizumab, an anti‐IL5 monoclonal antibody, has already been approved for allergic asthma." (PMID 35620572, 2022). "Among Th2 cytokines, IL‐5 and IL‐13 have multiple functions in the development of allergic asthma." (PMID 35344296, 2022). "IL-5 plays a key role in the differentiation, maturation, chemotaxis and activation of eosinophils and often cooperates with IL-4 to upregulate the level of eosinophils in patients with allergic asthma." (PMID 35744915, 2022). "However, in a ragweed murine model of allergic asthma, administration of IL-18 together with the allergen increased the production of IL-5 by splenocytes cultured in the presence of ragweed." (PMID 33803752, 2021). "We extracted total RNA from the lung tissue of mice from both the control and the F2-administered groups in the allergic asthma model and examined the changes in the Th2 cytokines IL-4, IL-5, and IL-13, eosinophil-recruiting chemokine CCL11 and allergic asthma-related cytokine IL-33 using RT-qPCR." (PMID 34576124, 2021). "ClusterB was highly linked to the Th2 immune response and had higher expression levels of TSLP, IL-33, IL-4, IL-5, and IL-13, which indicated that clusterB may be related to allergic asthma." (PMID 33763115, 2021). "In addition, P. cocos extract markedly suppressed Th2cytokines, IL-4, IL-5, and IL-10, secretions that have been suggested as a potential therapeutic target in allergic asthma." (PMID 33919400, 2021). "Therefore, the higher secretion of IL-4, IL-5, and IL-13 contributes substantially to inflammation in allergic asthma." (PMID 32617136, 2020). "To explore how TLR2 agonist and miR146a-mimic attenuate OVA-induced allergic asthma, we considered Th1 cytokines, including IgE, IL-4, IL-5 and IL-13, might be involved." (PMID 32600285, 2020). "The pathogenesis of allergic asthma involves Th2-type cytokines, such as IL-4, IL-5, and IL-13." (PMID 32915886, 2020). "Elevated levels of IL-4 and IL-5 are present in BAL of patients with allergic asthma." (PMID 31772507, 2019). "This may result in the creation of a local, IL-5 rich inflammatory state similar to that observed in allergic asthma." (PMID 29859068, 2018). "The Th2 cytokines, IL-4, IL-5, and IL-13, were increased in patients of allergic asthma." (PMID 29086354, 2018). "The characteristic features of allergic asthma, including airway hyperreactivity, histopathology, cytokines (IL-4, IL-5, IL-13, IL-17, and INF-γ), and CD4+CD25+Foxp3+Treg cells in bronchoalveolar lavage fluid (BALF), and downstream proteins of mTORC1/2 signaling were examined." (PMID 29234390, 2017). "In addition, it has been reported that the administration of 5 mg/mL of hesperidin in a mouse model of allergic asthma inhibited the IL-4 production in splenocytes and the IL-5 concentration in the bronchoalveolar fluid." (PMID 28587283, 2017). "Moreover, the sputum IL-5 levels at 7 h and 24 h after bronchial challenge were significantly higher in the patients with allergic asthma than those with allergic rhinitis." (PMID 25829869, 2015). "The molecules produced by E. granulosus which down-regulate the Th17 and IL-5 responses may prove useful agonists for prevention and treatment of allergic asthma." (PMID 25409540, 2014). "Moreover, Th2 cytokines such as IL-4, Il-5 and IL-13 are crucial for the pathogenesis of allergic asthma." (PMID 24671176, 2014). "Moreover, CD34+ cells producing IL-5 and IL-13 are detected in the sputum of individuals with allergic asthma." (PMID 24822215, 2014). "However, several reports have shown increased production of IFN-γ in addition to IL-4 and IL-5 in allergic asthma." (PMID 21810230, 2011). "Similarly, nanobodies that target the TH2 pathway (e.g., cytokines such as IL-5 and IL-13) could be delivered to the lungs to treat allergic asthma." (PMID 39062843, 2024).
allergic asthma (continued). "One explanation is that IL-31 is one of these Th2-type cytokines that induce inflammation-related cytokines, such as IL-4, IL-5 and IL-13, which form the complex network of cytokines that governs the development allergic asthma and so that role of IL-31 may be covered by other stronger cytokines." (PMID 30647024, 2019). "While IL-4 and IL-5 promote isotype switching of B cells to IgE producing cells and the infiltration of target tissues by eosinophils, IL-13 induces metaplasia of epithelial cells into goblet cells which is responsible for mucus hypersecretion in allergic asthma." (PMID 26999446, 2016). "Thus, inflammatory pathways underlying IL-5 alone are not sufficient for the development of AHR in allergic asthma." (PMID 25849971, 2015). "Hence, CF may act as a potential Th2 cytokine (IL-5) antagonist and have a therapeutic effect on allergic asthma." (PMID 22439901, 2012). "Hence, HPN may act as a potential Th2 cytokine (IL-5) antagonist and may have a therapeutic effect on allergic asthma." (PMID 21772663, 2011). "Once activated, for example by IL-33 or IL-22, ILC2 secrete IL-5 and IL-13, contributing to AHR and airway inflammation in OVA-induced allergic asthma." (PMID 40095032, 2025). "Early studies in murine allergic asthma models have shown that depletion of CD4 + CD25+ Tregs enhances neutrophil and T‐cell recruitment to the airways, IL‐4 and IL‐5 production, and airway hyperreactivity." (PMID 40497455, 2025). "GATA3 has previously been shown to have strong links to allergic asthma and the promotion of Th2 differentiation and the resulting release of cytokines regulating ASM contractility, including IL-13 and IL-5." (PMID 40131902, 2025). "The role of IL-4, IL-5, IL-6, IL-33, TNF-α and IFN-γ in the pathogenesis of allergic asthma is well documented has been elaborately explicated elsewhere." (PMID 38807596, 2024). "Eosinophil infiltration and IL-4, IL-5, and IL-13 expression levels were also similar in HDM-induced allergic asthma LysMCreCul5fl/fl mice and Cul5fl/fl mice." (PMID 38177117, 2024). "The Th2-like cell responses and cytokines, including IL-4, IL-5, IL-13, and TNF-α, play a central role in the immunological pathway in patients with allergic asthma." (PMID 38765484, 2024). "In an allergic asthma model, IRF7 mediated the activation and function of ILC2s cells through BCL11B, increasing the expression of IL-5 and IL-13, which in turn promoted allergic respiratory inflammation and allergic asthma." (PMID 37251373, 2023). "In the present study, a widely used allergic asthma mouse model has been established, in which the levels of IgE, TNF-α, and IL-5 are successfully upregulated by OVA compared with the NC control." (PMID 35371026, 2022). "To further reveal the relationship between m6A patterns and allergic asthma, we investigated the correlation between m6A patterns and thymic stromal lymphopoietin (TSLP), interleukin (IL)-33, IL-4, IL-5, and IL-13." (PMID 33763115, 2021). "Characteristic of allergic asthma, CD4+Th2 lymphocytes secrete Th2 cytokines, interleukin (IL)-4, IL-13, and IL-5 that mediate the inflammatory immune response." (PMID 32477356, 2020). "In addition, SG treatment could alleviate allergic asthma by reducing the inflammatory cells in bronchoalveolar lavage (BAL) fluid and by decreasing inflammatory factors, including IL-4, IL-5, IL-13, eotaxin, and IgE, which are linked with the decreased expression of iNOS and COX-2." (PMID 31572487, 2019). "Oral administration of L. plantarum KTCT3104, L. curvatus KTCT3767, and Lactobacillus reuteri ATCC23272 was shown to alleviate allergic asthma by inhibiting AHR and reducing the production of Th2 cytokines, such as IL-4 and IL-5 in BAL fluids." (PMID 31231389, 2019). "This was accompanied by overexpression of intracellular IL-5 and ST2 by sputum HPC indicating increased activation of these cells in eosinophilic COPD, analogously to allergic asthma." (PMID 29859068, 2018).
allergic asthma (continued). "IL-5, IL-3, and GM-CSF are present in bronchoalveolar lavage (BAL) fluid from subjects with mild allergic asthma and are increased after segmental lung antigen challenge." (PMID 30048528, 2018). "Allergic asthma is an inflammatory airway disorder mediated by TH2 cells, which produce various effector cytokines (IL-4, IL-5, and IL-13)." (PMID 29696026, 2018). "We also evaluated serum IgE production and Th2 inflammatory molecules generated by CKA-induced allergic asthma to ensure that MMDT inhibited the secretion of IgE and BALF inflammatory cytokines IL-4, IL-5, and IL-13." (PMID 24723965, 2014). "In the present study, ST36 EA stimulation suppressed the increased antigen-specific IgE production and Th2 cytokines such as IL-4, IL-5, and IL-13 in OVA-induced allergic asthma mice." (PMID 22649477, 2012). "We also evaluated serum IgE production and Th2 inflammatory molecules generated by OVA-induced allergic asthma to ensure that EA decreased the levels of IgE and BAL fluid inflammatory cytokines, IL-4, IL-5, and IL-13." (PMID 22649477, 2012). "Pro-inflammatory factors such as IL-5, IL-13, TNF-α, and IL-6 play a leading role in the pathogenesis of allergic asthma, including the growth of eosinophils, the isotypic transition of B cells to IgE production, chemotaxis of neutrophils, and bronchial contraction." (PMID 39408735, 2024). "Although they are few in number in circulating blood and lungs of healthy individuals, eosinophils are more frequent in allergic asthma and allergic bronchopulmonary aspergillosis (ABPA), as well as the Th2 cytokine repertory, comprised principally by IL-5 and IL-13." (PMID 36145419, 2022). "In conclusion, our results suggests that estrogen can play a protective role in allergic asthma by negatively regulating IL-33 induced ILC2 and IL-5/IL-13 cytokine production, furthermore we demonstrated that this effect is regulated by NF-κB signaling pathway." (PMID 36506643, 2022). "Paeoniflorin can reduce the expression levels of IL-5, IL-13, IL-17, and eotaxin in the OVA-induced allergic asthma mice model, which may be concerned with the blocking of the MAPK pathway activation." (PMID 35431951, 2022). "Furthermore, MX1, RSAD2, IFIT1, IFI27, OAS3, and SAMD9L levels correlated positively with IL-5, IL-13, and MUC5AC levels, which are the key mediators of allergic asthma." (PMID 36211429, 2022). "Although anti-IL-5 or anti-IL-5Rα mAbs have therapeutic effects on patients with allergic asthma and eosinophilia, no therapeutic effects were observed in patients with moderate or neutrophilic asthma." (PMID 34576124, 2021). "Overall, the results of immune profile analysis showed that PGT treatment reduced the populations of IL-5 and IL-13 producing immune cells, such as CD4+ T cells and ILCs, as well as the total amount of IL-5 and IL-13 producing cells in OVA-induced allergic asthma." (PMID 33374657, 2020). "We confirmed that the OVA-induced allergic asthma is mainly driven by the Th2 response, following the production of IL-5 and IL-13, but not IL-4, and that PGT treatment greatly reduced such induction." (PMID 33374657, 2020). "A previous study indicated that FMT 10 mg/kg administrated by intraperitoneal injection could significantly alleviate AHR and decrease Th2 cytokines (IL-4, IL-5, and IL-13) levels in the HDM-induced inflammation of allergic asthma." (PMID 33013383, 2020). "IL-5 is an excellent target for the treatment of allergic and non-allergic asthma with an eosinophilic component." (PMID 30405579, 2018). "IL17A, IL33, and IFNγ levels were significantly elevated in allergic and nonallergic asthmatics when compared to control, whereas IL5 levels were elevated only in patients with allergic asthma when compared to control." (PMID 30306094, 2018). "In non-allergic asthma, omalizumab is not indicated, while an anti-IL5/IL5Rα, dupilumab, or tezepelumab could be considered." (PMID 36452259, 2022).
allergic asthma (continued). "The unbalance of Th1/Th2 cells response in allergic asthma shows that the IL-4, IL-5, and IL-13 and its respective transcription factor STAT6 remains intensely upregulated at the expense of a drastic decrease of T-bet levels in the airway of individuals with allergic asthma." (PMID 36685604, 2022). "In addition, previous research has shown that circulating IL-5, but not local IL-5, is required for the development of an allergic asthma model." (PMID 34576124, 2021). "While anti-IL-5 treatment has been widely approved for treating eosinophilic asthma, attenuation of broad-range inflammatory and physiological changes after allergen challenge suggests that blocking CCR3, IL-3, and GM-CSF are also important targets for the management of allergic asthma." (PMID 33917396, 2021). "ILC2 mainly produced IL-5 and IL-13, but not IL-4, in an allergic asthma model." (PMID 32915886, 2020). "Our data showed the Lineage-cells from both mugwort-allergic asthma group and HDM-allergic asthma group could produce significant amounts of IL-5 and IL-13 after the stimulation with IL-33 when compared to IL-2 alone (all P < 0.05, respectively), or medium alone (all P < 0.05, respectively)." (PMID 29449864, 2018). "Likewise, the absence of Mrp4 did not affect the release of the cytokines IL-4 and IL-5, which both play an essential role during allergic asthma." (PMID 23613808, 2013). "Interestingly, the midpregnancy cytokine profile we describe in the ASD group in the present study (increased IL-4, IL-5 and IFN-γ) may be consistent with an allergic asthma clinical phenotype." (PMID 21810230, 2011). "Indeed, the most recent studies suggest as therapy of choice Omalizumab use for T2 high allergic asthma and IL-5 blockers or Dupilumab use for T2 high non-allergic eosinophilic asthma considering the method of administration, the frequency of treatment and the clinical improvement as well." (PMID 34209312, 2021). "Therefore, in those subjects, HPC may act as effector cells in an analogous way to allergic asthma, by fostering the development of a local IL-5 rich environment independent of the IgE pathway." (PMID 29859068, 2018). "Nonetheless, since Th2 cells are not the only source of Th2 cytokines in the lungs in allergic asthma, AHR and lung secretion of IL-4 and IL-5 induced by OVA was increased in both A/J and BALB/c." (PMID 34924814, 2021). "We further identified that the sorted ILC2s produced IL-5 and IL-13, and demonstrating there was a positive correlation between IL-13+ILC2s numbers and FeNO levels in pollen-allergic asthmatics, however, no similar results were found in HDM-allergic asthma patients." (PMID 29449864, 2018).
nasal polyps (137 papers, 2006 to 2026). "When stratifying by CRS with nasal polyps, elevated levels of nasal IL-5 were associated with increased rates of response." (PMID 40648819, 2025). "Similar to NETs, developed in the tissue of nasal polyps, primarily in subepithelial regions with epithelial barrier defects, and are associated with linked to elevated tissue levels of IL-5 and S. aureus colonization." (PMID 37934391, 2023). "These environments are common during the formation of nasal polyps associated with aspirin intolerance, which is also marked by an increase in inflammatory mediators, especially IL-4, IL-5, and IL-13." (PMID 36721412, 2023). "Other studies have also shown that increased expression of IL-5 at both the mRNA and protein levels has been identified in nasal polyps compared with sinus mucosa, and is associated with the need for revision surgery and nasal polyposis." (PMID 36832203, 2023). "We identified IL-5-producing ST2hi pathogenic Th2 cells (Tpath2 cells) that likely induce eosinophilic inflammation in nasal polyps of Eosinophilic Chronic Rhinosinusitis (ECRS) patients." (PMID 30315197, 2018). "Nasal polyps are benign lobular-shaped growths that project in the nasal cavities; they originate from inflammation in the paranasal mucous membrane and are associated with a high expression of interleukins (IL)-4, IL-5, IL-13, and IgE." (PMID 33287173, 2020). "Furthermore, IL-5-dependent eosinophilic inflammation has been shown to significantly correlate with epithelial damage, smell loss, fibroblast activity, collagen production, and the deposition of fibrotic tissue within nasal polyps." (PMID 37240477, 2023). "AE in chronic rhinosinusitis with nasal polyps (CRSwNP) was associated with increased expression of mucus cytokines including myeloperoxidase (percentage increase [PI] = 101%), IL-5 (PI = 125%), and IL-6 (PI = 162%) and could be predicted by the increasing mucus cystatin and periostin." (PMID 32811568, 2020). "The type 2 cytokines IL-4, IL-5, and IL-13, as well as IgE and eosinophils, play essential roles in sustaining inflammation and promoting the formation of nasal polyps." (PMID 39962262, 2025). "ILC2s are enriched in nasal polyps from chronic rhinosinusitis patients and skin biopsies from atopic dermatitis patients and are among the main producers of IL-5 and IL-13 in the lungs of asthmatic patients." (PMID 39962262, 2025). "There was a strong positive correlation between ILC2s and IL‐5 in nasal polyps (r = .755, p < .001)." (PMID 38888464, 2024). "For example, it was found to be increased on immune cell populations in the nasal mucosa of allergic rhinitis patients and correlated with disease severity and IL-5 levels in chronic rhinosinusitis with nasal polyps." (PMID 38318168, 2024). "The airway epithelium actively influences immune responses by secreting alarmins such as TSLP, which, when released from nasal polyps, provokes a heightened IL-5 response from mast cells." (PMID 38680486, 2024). "Nasal polyps with eosinophils infiltration are accompanied by type-2 inflammation expressing IL-4, IL-5, and IL-13 and high levels of circulatory but particularly local IgE." (PMID 37674852, 2023). "A recent study found that Tnfsf11 was able to induce IL-5 and IL-13 in ILC2s via Tnfsf11a in chronic rhinosinusitis with nasal polyps." (PMID 37228603, 2023). "Within such an airway context, type 2 asthma and nasal polyposis develop as a consequence of the overexpression of IL-4, IL-13, and IL-5." (PMID 37240477, 2023). "Staphylococcus aureus superantigens contribute to the polarization of type-2 immune response in nasal polyp tissue characterized by Th2 cytokines (IL-4, IL-5, IL-13) production and promote eosinophils infiltration." (PMID 37674852, 2023). "Corticosteroids (both intranasal and oral) have been associated with significant reductions in eosinophil numbers as well as with reductions in ECP and IL-5 levels in nasal polyps." (PMID 37046572, 2023).